CCL20 (C-C motif chemokine ligand 20)
Diseases named in the same sentence as CCL20 in open-access papers (continued):
Sharing a sentence is not in itself a finding about the gene and the disease.
tumor (continued). "Targeting Gal1 dampened the secretion of CCL20 and inhibits the recruitment of Tregs, thereby activating anti‐tumor immunity and ameliorating anti‐PD‐1 resistance." (PMID 39853961, 2025). "In parallel, TNF-β and chemokines like CCL3 and CCL20 are critical for orchestrating immune cell recruitment and enhancing tumor surveillance." (PMID 40860824, 2025). "CCL20 is that contributes to tumor evasion by recruiting Tregs and Th17 cells to the tumor niche, promoting EMT transition and is a negative prognostic for immunotherapy treatment." (PMID 40589738, 2025). "In general, cervical cancer expresses high amounts of CCL20 which enhances infiltration of Th17 cells into the tumor mass." (PMID 40136652, 2025). "In colorectal cancer, for instance, F. nucleatum enhances macrophage infiltration and promotes the polarization of macrophages towards the M2 phenotype in a CCL20-dependent manner, contributing to tumor metastasis." (PMID 39921821, 2025). "Consistent with this, the CCL20 level in orthotopic tumor tissues measured by ELISA demonstrated similar trends." (PMID 39853961, 2025). "In colorectal cancer, Fusobacterium nucleatum plays a critical role in tumor progression by modulating the miR-1322/CCL20 axis." (PMID 39973938, 2025). "Collectively, our findings proposed that CCL20 secreted by HPV-infected KRT15high tumor cells promoted TLS formation, thereby enhancing anti-PD-1 therapy responses in HPV+HNSCC." (PMID 41462011, 2025). "HPV infection reduces DC percentages in cancer lesions and inhibits CCL20 expression, which is crucial for DC recruitment to the tumor." (PMID 40136652, 2025). "mRNA levels of GLI1 or CCL20 were found to be significantly elevated in tumour tissues compared to paired adjacent non‐tumour liver tissues." (PMID 40913253, 2025). "In contrast, administering CCL20 via intratumoral injection in subcutaneous HCC mouse models restored tumor growth, reduced the CD8+ T cell infiltration, increased the frequency of CD4+CD25+Foxp3+ Tregs and CCR6+ Tregs in shGal1 tumors." (PMID 39853961, 2025). "In renal cell carcinoma tumor microenvironment, macrophage-mediated CCL20 via AKT activation promoted the migration of cancer cells through EMT induction." (PMID 39985603, 2025). "mDCs recruitment into the TME has been reported to depend on the CCR6/CCL20 axis, the latter of which showed a significant increase of expression in tumor tissues (logFC=3.5)." (PMID 40552117, 2025). "Emerging evidence suggests that CCL20, a chemokine secreted by tumor cells, facilitates the recruitment and polarization of macrophages toward an M2 phenotype, thereby promoting a protumorigenic and immunosuppressive microenvironment." (PMID 41312091, 2025). "Highly expression of CCL20 promotes the migration and proliferation of cancer cells, as well as remodels the tumor microenvironment to accelerate cancer progression." (PMID 40191203, 2025). "In conclusion, our findings suggested that tumor‐derived Gal1 promoted the secretion of CCL20 by TAMs, thereby recruiting Tregs as collaborators in tumor development and impeding the function and infiltration of CD8+ T cells." (PMID 39853961, 2025). "This insufficient vascularization is often accompanied by low levels of chemokines such as CCL4, CCL5, and CCL20, which are essential for recruiting dendritic cells to the tumor site for effective antigen presentation." (PMID 41149836, 2025). "The chemokine receptor CCR6, and its ligand CCL20 have been described to play a role in tumor progression in several cancers." (PMID 39825956, 2025). "Tumour growth in mice was inhibited in mice implanted with GLI1 KO or CCL20 KO cells compared to those with WT cells." (PMID 40913253, 2025). "We isolated RT-MPs from irradiated tumor cell supernatants and found that RT-MPs upregulated Ccl20 expression in BMDMs, whereas RT-MP-depleted conditioned medium lost this capacity." (PMID 41055972, 2025).
tumor (continued). "In this study, we demonstrated that miR-183-5p derived from HCC cell-derived EVs induces endothelial cell angiogenesis, facilitating crosstalk between tumor and endothelial cells through the CCL20/CCR6 axis, thereby promoting HCC progression." (PMID 40115013, 2025). "HCC cell-derived CCL20 can directly promote the accumulation of TAMs in the tumor immune microenvironment (TIME), which subsequently leads to a reduction of CD8+ T cells." (PMID 39755756, 2025). "Collectively, the activation of the PI3K‐AKT‐NF‐κB pathway in TAMs induced by tumor‐derived Gal1 was a significant contributor to the secretion of CCL20 and the recruitment of Tregs in HCC." (PMID 39853961, 2025). "At the end of the animal experiment, the mice were sacrificed, and tumours bearing GLI1 KO or CCL20 KO cells exhibited reduced size and weight relative to WT controls." (PMID 40913253, 2025). "CCR6 is expressed in melanoma cells, in vivo addition of CCL20 leads to tumor growth and progression." (PMID 39825956, 2025). "In recent years, research has confirmed that the CCL20/CCR6 axis plays a critical role in promoting tumor growth in the tumor chemokine network." (PMID 40145607, 2025). "Within primary cutaneous melanoma specimens CCR6 is localized to the tumor area and CCL20 to the stroma." (PMID 39825956, 2025). "Collectively, CCL20 critically shapes the inflammatory landscape, orchestrates immune cell recruitment/regulation, and mediates bacterium-tumor crosstalk in OSCC." (PMID 41445742, 2025). "The released CCL20 recruits monocytes into the tumour microenvironment by interacting with its receptor, CCR6." (PMID 40913253, 2025). "The upregulated chemokines can attract a diverse range of innate and adaptive immune cells, for example, CCL2 attracts tumor-associated macrophages, CXCL10/11 attracts CD8+ T cells, CCL20 attracts dendritic cells, and CXCL5 attracts neutrophils." (PMID 40689422, 2025). "The effect of GLI1 and CCL20 on tumour growth and monocyte infiltration was evaluated using a xenograft mouse model." (PMID 40913253, 2025). "In tumor-bearing mice, injection of anti-CCL20 suppressed Treg-mediated tumor growth and sensitized tumors to 5-FU treatment." (PMID 39985603, 2025). "The overexpression of CCL20 in normal tissues adjacent to adrenal metastases establishes a microenvironment that enhances the attraction of circulating tumor cells expressing CCR6 to the adrenal gland." (PMID 39328239, 2024). "Consistently, CCL20 expression has been confirmed to be tightly regulated by NF-κB and of special importance in facilitating tumor growth and metastasis through interacting with CCR6 in CRC." (PMID 38228802, 2024). "The coordinated actions of CCR6 and CCL20 contribute to tumour progression by exerting multiple functions on both HCCs and ECs." (PMID 38493218, 2024). "The understanding of the mechanisms behind the actions of CCL20 is important to develop new therapies for tumor patients." (PMID 38730689, 2024). "CCL20 has been reported to indirectly promote tumour progression by recruiting Treg, Th17 and Th22 cells in order to maintain a microenvironment of development and immunosuppression." (PMID 38363001, 2024). "Consistent with this, both CCR6 and CCL20 exhibited significant upregulation in tumor tissues compared to their matched normal counterparts in LUAD patients." (PMID 38551001, 2024). "In this study, bioinformatic and IHC analyses revealed that CCL20 was aberrantly elevated in tumour tissues compared with the normal tissues, and highly expressed CCL20 resulted in low OS, PFI and DSS rates." (PMID 38493218, 2024). "Altogether, our data support the idea that Cat D deletion controls TAM polarization from immune-suppressive M2 to immune-stimulatory M1 subtypes through TGFBI and CCL20 secretion, which in turn leads to suppression of tumor metastasis and growth." (PMID 38297161, 2024). "Extensive studies discussed the crucial role of NF-κB/CCL20 axis in tumor growth and metastasis, including CRC metastasis." (PMID 38228802, 2024).
tumor (continued). "CCL20, a chemokine, attracts immune cells such as T cells and dendritic cells into the tumor microenvironment through its receptor CCR6." (PMID 39164192, 2024). "IL‐17A and TNF synergistically induced the Th17‐promoting cytokines IL‐6 and IL‐1β as well as the Th17‐attracting chemokine CCL20 in mesothelial cells, indicating a reciprocal crosstalk that potentiates the tumor‐promoting role of Th17 cells in OC." (PMID 38566518, 2024). "In the H group, there were also a few specific interactions, such as the interactions between the dendritic cell-expressed ligands CCR6 and CXCR3 with the tumor cells-expressed receptor CCL20." (PMID 39268081, 2024). "Th9 cells are known to elicit strong host antitumor CD8+ cytotoxic T lymphocyte (CTL) responses by promoting Ccl20/Ccr6-dependent recruitment of dendritic cells to tumor tissues via IL-9 production." (PMID 39187636, 2024). "It has been reported that in a variety of cancers, CCR6+ tumor cells can migrate to CCL20 enrichment sites and promote tumor metastasis." (PMID 39324138, 2024). "Specifically, F. nucleatum promotes endothelial adhesion and extravasation of tumour cells and contributes to expression of tumour-derived CCL20, which is conducive to M2 macrophage infiltration, resulting in metastasis of colorectal cancer (CRC)." (PMID 38536233, 2024). "CCL20 can induce the accumulation of immature DCs so that the body cannot initiate the immune response against the tumor." (PMID 38765128, 2024). "Tumor-associated pDCs (TA-pDCs; i.e. into the tumor milieu or tumor-draining lymph nodes) are recruited at the tumor site by chemokines (e.g. CXCL12 and CCL20) released by cancer cells or by the TME." (PMID 39020402, 2024). "High expression of VDR in PAAD promotes M2 macrophage polarization and recruitment through the secretion of CCL20, which activates tumor progression." (PMID 38600588, 2024). "Clinically, CCL20 mRNA expression levels in tumor tissue were higher than those in normal tissue in the majority of CRC patients." (PMID 38902257, 2024). "Specifically, CCL20 has been reported to recruit chemotactic Tregs towards tumor microenvironment to promote tumorigenesis." (PMID 39042313, 2024). "Numerous studies have indicated that CCL20 contributes to tumour cell invasion and metastasis through the activation of the NF‐κB signalling pathway." (PMID 38809918, 2024). "Studies have shown that SMAD4 exerts its tumor-suppressive effects in CRC by downregulating the expression of the key inflammatory mediator CCL20." (PMID 39164192, 2024). "These facts are in accordance with our previous research, carried out in this same cohort of patients, describing tumor infiltration by Th1/17 and Tc17 cells and elevated circulating levels of CCL20." (PMID 39408071, 2024). "Meanwhile, tumour cells secrete various growth factors, including CCL20, which can bind to its specific receptor, CCR6, to accelerate the development of cancer by inducing angiogenesis." (PMID 38493218, 2024). "These cells display characteristics that foster tumor progression, marked by elevated CCL20 expression." (PMID 38571964, 2024). "Some studies have suggested that tumor-derived factors CCL20 or GM-CSF induce PD-L1 induction on neutrophils." (PMID 38534755, 2024). "In the Pan02 cell line overexpressing VDR, knockdown of CCL20 resulted in a deceleration of tumor cell proliferation in vivo and a reduction in the M2/M1 ratio." (PMID 38600588, 2024). "Conversely, in the Pan02 cell line with knockdown of VDR, the rate of tumor cell proliferation in vivo was partially restored following overexpression of CCL20." (PMID 38600588, 2024). "For instance, it has been demonstrated that chemokine (C-C motif) ligand 20 (CCL20) derived from tumor cells interacts with chemokine receptor 6 (CCR6) highly expressed by CD19+ CD5+ B cells, potentially enhancing angiogenesis and promoting HCC development." (PMID 38791916, 2024).
tumor (continued). "Tumor cell-secreted CCL20 and CCL22 in the pleural effusion act on the corresponding receptors CCR4 and CCR6 on Th17 cells and recruit them." (PMID 37680632, 2023). "Statistically insignificant correlations were observed between CCR6 and CCL20 mRNA expression levels and tumor size (p > 0.05, Kruskal–Wallis test)." (PMID 37316552, 2023). "When CCL20 is secreted in tumor tissues, it attracts CCR6-expressing Treg cells, which are involved in tumor progression and poor prognosis." (PMID 37218898, 2023). "CCL20 expression was significantly increased in tumours compared to normal and metastatic colon tissue (post hoc Dunn test, p = 3.16 × 10−56 and p = 4.39 × 10−3, respectively)." (PMID 36835258, 2023). "At the same time, that of FABP5, SCD, and CCL20 were upregulated considerably in TCGA HCC compared with non-tumor tissues." (PMID 36950134, 2023). "A previous study found that combining tumor cells expressing CCL20 followed by DC vaccination yielded strong anti-tumor responses." (PMID 37505292, 2023). "Plasmacytoid DCs were proposed to be attracted to the tumor microenvironment through the CCL20/CCR6 axis or the hypoxia and hypoxia inducible factor-1α (HIF-1α) pathway." (PMID 37958800, 2023). "There is also a study using online databases that have found significantly higher expression of CCL20 in HCC tissues compared to the adjacent non-tumor tissues." (PMID 37545521, 2023). "Several studies showed an effect for CCL20 signaling in enhancing tumor growth, invasiveness, and chemoresistance by recruiting Tregs and/or Th1778,79." (PMID 36750562, 2023). "The aim of present study was to assess changes in both the expression levels of CCR6 and CCL20 in tumor tissue of NSCLC patients and the expression level of miR-150, that is known to regulate the expression level of CCR6 according to data-base mirTarBased." (PMID 37316552, 2023). "We found that CCL20 knockdown combined with SLC7A2 overexpression significantly lessened the tumor volume." (PMID 36969014, 2023). "We focussed on endoglin, enolase γ, VEGF, IL‐6 and CCL20 which were all enriched in TSC2‐ EVs, compared to TSC2+ EVs, due to known associations with tumour‐promoting functions." (PMID 37337371, 2023). "CXCL10 and CCL5 chemokines were reported to stimulate CD4+ and CD8+ lymphocyte migration into the intra-tumor and stromal compartment, and CCL20 drove brain infiltration of Treg cells." (PMID 38239560, 2023). "CCL20-modulated PMN-MDSCs obviously promoted tumor sphere formation, and the mRNA expression levels of four stemness-related genes in primary mammosphere were remarkably increased." (PMID 36859354, 2023). "Upregulation of CCL20 secretion in senescent tumor cells was further validated by RT-qPCR quantification of mRNA expression and ELISA quantification of protein." (PMID 37398643, 2023). "Ccl20 exhibits almost no hydrophobic regions on its surface and has strong antimicrobial activity, while transgenic tumor cells of ccl20 also inhibit tumor growth." (PMID 37238005, 2023). "Lastly, FISH and IHC were used for validation of CCL20 expression in patients’ specimens and U14 subcutaneous tumor models were built for TME composition." (PMID 37183243, 2023). "Contributes to tumor infiltration of Treg lymphocytes in a chemokine (especially CCL20)-dependent fashion, promoting aggressive tumor behaviors." (PMID 37691931, 2023). "Fusobacterium nucleatum induces the expression of tumor-derived C-C motif chemokine ligand 20 (CCL20), promotes the recruitment of macrophages and MDSC in the TME, and transforms macrophages to the M2 type." (PMID 36950522, 2023). "Our study confirmed that smoking significantly changes the level of CCL20 mRNA expression in tumor tissue in NSCLC patients." (PMID 37316552, 2023). "In summary, senescent tumor cells secrete CCL20 to induce immunosuppressive M2 polarization, while complement derived from non-senescent tumor cells stimulates M1 antigen presentation and antitumor immune responses." (PMID 37398643, 2023).
tumor (continued). "Previous studies have also shown that the immune chemokines CXCL3 and CCL20 also play an important role in tumour growth, invasion, and migration." (PMID 37919768, 2023). "CCL20 can contribute to tumor progression by modulating the functions and phenotype of immune cells in the TME, particularly by inducing PD-L1 expression on neutrophils." (PMID 37762335, 2023). "Higher expression level of CCL20 mRNA but lower expression level of CCR6 mRNA were observed in tumor in comparison to control tissue." (PMID 37316552, 2023). "The CCL20 that tumor cells release encourages the migration and growth of neighboring breast cells and the initiation of BC." (PMID 37373025, 2023). "CCL20 promotes the attraction of CCR6+ T cells to tumor sites expressing CCL20 and CCR6+ cancer cells to metastatic sites with abundant CCL20." (PMID 37092451, 2023). "CCL20 was indicated as inducer of dampened anti-tumor ability of CTL when it was secreted by macrophages." (PMID 37183243, 2023). "VCAN, THBS1, and CCL20 were highly expressed in the Mono_2 cluster, which was derived from tumor tissue, indicating the potential of this specific monocyte cluster to exert a critical immunosuppressive effect." (PMID 37533434, 2023). "Observing the expression pattern among all major cell types, the expression of CDKN2A and CCL20 are highly correlated and ubiquitous to malignant ductal 2, suggesting the key role of senescent tumor cells as secretor of CCL20 in the tumor TME." (PMID 37398643, 2023). "Low expression of miR-150 is also associated with tumor invasion induced by CCL20 and IL22, which lowers anti-tumor immunity and protects stemness." (PMID 36831498, 2023). "A higher expression level of CCL20 mRNA was observed in tumor tissue than control tissue (median RQ: 0.726 and 0.369, respectively)." (PMID 37316552, 2023). "Th17 cells can stimulate CD8 + CTL response through IL-2 and pMHC I, and stimulate the expression of CCL2 and CCL20 in tumor microenvironment to promote the recruitment of various inflammatory leukocytes (DCs, CD4 + and CD8+ T cells)." (PMID 36874093, 2023). "Tumor-cell-derived CCL20 interacts with B lymphocytes and promotes HCC progression via enhancing angiogenesis." (PMID 36982370, 2023). "After 30 days, we measured the tumor weight and observed that tumor weight was distinctly lowered by CCL20 knockdown combined with SLC7A2 overexpression." (PMID 36969014, 2023). "Mo0 stimulated the release of cytokines and chemokines such as IL6, IL1A, CXCL1, CXCL5, and CCL20, which can induce monocyte recruitment to tumor." (PMID 37675100, 2023). "Astrocytic CCL20 promotes glioma cell invasion through the increase in tumor cell expression of the hypoxia-inducible factor HIF-1α." (PMID 38293652, 2023). "Cisplatin induces an increase in CCL20 and IL-1β in tumor cells within a cold tumor model, both of which activate ILC3s to release the chemokine CXCL10, attracting CD4 T and CD8 T lymphocytes to infiltrate tumor tissue and then exert anti-tumor effects." (PMID 37122757, 2023). "Studies have shown that CCL20 accelerates tumor metastasis by inducing epithelial-mesenchymal transformation (EMT), and inhibiting T cell proliferation, and promoting the amplification of immunosuppressive Treg cells." (PMID 37059586, 2023). "We showed that blocking one such signaling axis using CCL20-blocking antibody significantly reduced tumor growth in a subcutaneous model of syngeneic PCa." (PMID 36750562, 2023). "This process is impaired in senescent tumor cells, which secrete CCL20 to favor M2 polarization and to abrogate antigen presentation, leading to an immune desert microenvironment." (PMID 37398643, 2023). "We noticed that the level of CCR6 mRNA expression negatively correlated with the growth of the tumor; however, the expression level of CCL20 mRNA was higher in larger tumors (T3 + T4 vs. T1 and T2)." (PMID 37316552, 2023).